CASP1 (caspase 1)
Diseases named in the same sentence as CASP1 in open-access papers (continued):
Sharing a sentence is not in itself a finding about the gene and the disease.
COVID-19 (86 papers, 2020 to 2026). A disease caused by infection with severe acute respiratory syndrome coronavirus 2. "Lung biopsies from deceased COVID-19 patients show Diffuse Alveolar Damage and vasculopathy associated with activated-caspase-1." (PMID 39882243, 2024). "The expression of caspase-4 in the lungs of COVID-19 patients showed an association with the levels of inflammasome activation markers such as caspase-1, IL-1β, IL-6 and IL-18." (PMID 37251383, 2023). "Other genes commonly associated with COVID-19 immune responses (e.g., Stat1, Myd88, Il1b Nlrp3, Cdkn1a, and Casp1) were also upregulated in responder brains." (PMID 36739463, 2023). "Higher levels of active caspase-1 (Casp1p20) in the sera of COVID-19 patients are associated with severe disease and poor clinical outcomes." (PMID 35265086, 2022). "IL1B, P2RX7, IFNB1, IFNB1, TNF, and CASP1 enhance the network connectivity between multiple sclerosis (MS) complex genomes associated with COVID-19 and NOD-like receptor (NLR) signaling." (PMID 36483456, 2022). "COVID-19 studies highlight the significant increase in pro-inflammatory factors that can also be found in the brain; in particular, in animal models, caspase-1 activation causes higher cleaved caspase-3 levels with consequent activation of IL-1β." (PMID 32973818, 2020). "In addition, COVID-19 studies have revealed the upregulated level of caspase-1 and its association with severe disease, longer hospitalization, and poor clinical outcomes." (PMID 36979955, 2023). "Caspase-1 is associated with immune-related COVID-19 pathogenicity and worse outcome." (PMID 36881624, 2023). "Since the corticosteroids dexamethasone and methylprednisolone assist in the recovery of severely infected COVID-19 patients needing respiratory support, it is of interest to analyze whether the inhibition of caspase-1 is implicated in these cases." (PMID 35163769, 2022). "RNH1 protein, an inhibitor of inflammasome activation through proteasome-mediated degradation of caspase-1, is increased in the blood and lung biopsies from individuals with COVID-19 and is negatively associated with SARS-CoV-2-mediated inflammation and adverse clinical outcomes." (PMID 35265086, 2022). "Thus, the caspase-1-mediated classical pyroptosis pathway may be an important cause of the vicious cycle of cytokine storm caused by the interaction between COVID-19 and RA disease." (PMID 36532040, 2022). "Exosomes isolated from hospitalized, severe COVID-19 patients, when exposed to human microvascular endothelial cells, significantly stimulated the mRNA expression of the inflammasome, caspase-1, and the pleiotropic cytokine, IL-1-beta." (PMID 40051620, 2025). "The interaction between COVID-19 and comorbidities (e.g., diabetes) can improve the inflammatory response, increasing the expression of inflammatory markers such as NLRP3, ASC and caspase-1, thus elevating the risk of severe complications." (PMID 40862415, 2025). "Our finding further supported the notion of strong activation of CASP1 in both COVID-19 and GBS patients at the transcriptomic level." (PMID 40433617, 2025). "Single-cell RNA-seq analysis showed upregulation of caspase-1 in CD4+ T cells from COVID-19 hospitalized patients compared to unexposed controls." (PMID 40051620, 2025). "Employing various algorithms, we identified MMP9, CAMP, and CASP1 as NETRGs, demonstrating good discriminatory capacity in COVID-19 and GBS." (PMID 40433617, 2025). "Transcriptional states of multiple caspases and expression of active caspase-1 in blood cells from COVID-19 patients in acute and convalescent stages of the disease were evaluated." (PMID 38543815, 2024). "To assess the consequences of NLRP3-inflammasome and caspase-1 activation in COVID-19 patients, we measured the levels of IL-1β, IL-1Ra and IL-6 in both BALF and serum of C-ARDS or NC-ARDS patients and in control subjects." (PMID 39882243, 2024).
COVID-19 (continued). "al. investigated caspase-1 activity in SARS-CoV-2 infection, including in red blood cells, given the significance of COVID-19-associated coagulopathies." (PMID 38543815, 2024). "In particular, NLRP3 and NLRP1 inflammasome activation—as well as the components of its signaling, i.e., CASP1, IL-1β, and IL-18, etc.—show a relationship with the inflammatory factors and disease progression in patients with COVID-19." (PMID 38612539, 2024). "A significant increase in NLRP3 and caspase-1 expression was observed in HPMVEC treated with COVID-19 serum compared to those treated with healthy serum." (PMID 38771750, 2024). "Both the NLRP3 subunit and caspase 1 (assessed using an antibody that detects both pro-caspase and activated caspase) were found to be significantly increased in patients with COVID-19." (PMID 38771750, 2024). "Caspase-1 activation and a predominant IL-1/IL-6 signature associated with IFNγ-induced chemokines remain highly detectable in the BALF of steroid-resistant COVID-19-ARDS, arguing for new multi-targeted therapeutics in COVID-19-ARDS." (PMID 39882243, 2024). "PAN-caspase inhibitor emricasan inhibits caspase-1 activity of CD4+ T lymphocytes in the peripheral blood of patients with moderate to severe COVID-19." (PMID 37465759, 2023). "In our study, placental expression of caspase-1 from patients with COVID-19 was high and was even higher if it was accompanied with preeclampsia." (PMID 37362630, 2023). "The COVID-19 group had the second poorest placenta damage (placental expression: caspase-3 [10.33±3.64], caspase-1 [5.71±4.29], and TNF-alpha [6.46±4.06])." (PMID 37362630, 2023). "Our work identified that CASP1, CD4, and EIF2AK3 were diagnostic genes of COVID-19 and correlated with immune activity." (PMID 37228369, 2023). "Cleaved caspase-1 and IL-18 were detected in the sera of COVID-19 patients and were positively correlated with disease severity, poor prognosis and other COVID-19 severity serum markers, including IL-6 and LDH." (PMID 36661317, 2023). "Some studies have reported an elevation in the proportion of monocyte forming specks, increased caspase-1 activity, and heightened production of IL-1β and IL-18 from peripheral blood mononuclear cells (PBMCs) in COVID-19 patients." (PMID 38140660, 2023). "Several COVID-19 studies have revealed that apoptotic caspase-1, -3, -8, and -9 are active during SARS-CoV-2 infections." (PMID 36979955, 2023). "The results suggest that CASP1 is more likely to be a valuable target for drug development against COVID-19." (PMID 37228369, 2023). "Monocytes from critically ill patients with COVID-19 exhibited higher caspase-1 activation than those from healthy controls." (PMID 37251383, 2023). "The myocardial injury caused by COVID-19 was associated with multiple inflammatory pathways, and IL6, NFKBIA, CSF1, CXCL1, IL1R1, SOCS3, and CASP1 were key genes of the inflammatory pathway." (PMID 37564653, 2023). "For instance, a decrease in caspase-1 activity at baseline in the PMN of hospitalized COVID-19 patients has been observed." (PMID 38140660, 2023). "The levels of active caspase-1 and IL-18 were higher in the sera of COVID-19 patients than the controls." (PMID 37251383, 2023). "Inflammatory mediators IL-1β and IL-18, the main cytokine products of caspase-1 activation, are observed to be increased in the lungs and sera of patients with symptomatic COVID-19 compared to asymptomatic patients and healthy individuals." (PMID 35265086, 2022). "The anti-inflammatory drug colchicine (which is reported in the literature to be a caspase-1 inhibitor) and the corticosteroid drugs, dexamethasone and methylprednisolone, are among the most effective active compounds for COVID-19 treatment." (PMID 35163769, 2022). "For COVID-19 treatment, the caspase-1 inhibitor, belnacasan (VX765), is recently considered to have the therapeutic potential." (PMID 35958114, 2022).
COVID-19 (continued). "In this study, we suggest that inhibition of caspase-1, an enzyme involved in triggering the release of pro-inflammatory cytokines, is relevant to the mechanism of anti-COVID-19 therapy." (PMID 35163769, 2022). "Activation of caspase-1 was noted in the endothelial cell culture medium following exposure to the COVID-19 exosomes." (PMID 35587188, 2022). "Using molecular mechanics docking techniques, this study shows that four well-known anti-inflammatory drugs, which all have activity against COVID-19, also show inhibitory effects on caspase-1." (PMID 35163769, 2022). "Firstly, active NLRP3 inflammasome and caspase-1 are detected in the peripheral blood and tissues of COVID-19 patients and are positively correlated with severity markers for COVID-19 (e.g., IL-6)." (PMID 36532040, 2022). "Caspase-1 activity is also upregulated in CD4+ T cells of COVID-19 patients that were hospitalized, those with liver disease, and long-haulers." (PMID 35265086, 2022). "Other caspase-1 inhibitors, such as belnacasan, have also been evaluated for the treatment of patients with mild to moderate COVID-19 (clinical trials NCT05164120)." (PMID 35997950, 2022). "Caspase 1 cleaves inactive pro-IL-1β to active IL-1β which is an important mediator for lung inflammation and fibrosis in COVID-19." (PMID 36422492, 2022). "We observed a significant induction of NLRP3, caspase-1, and interleukin-1β (IL-1β) mRNA expression in endothelial cells following exposure to exosomes from severe COVID-19 patients compared with that from patients with mild disease or healthy donors." (PMID 35587188, 2022). "A Western blot analysis revealed a significant increase of cleaved caspase-1 in severe COVID-19 exosome-exposed HMEC-1 cells as that compared with exosomes from normal healthy subjects." (PMID 35587188, 2022). "This process also indirectly demonstrates a potential caspase-1-directed pyroptosis and a shared pro-inflammatory mechanism between COVID-19 and RA, which requires further basic and clinical research." (PMID 36532040, 2022). "The NLRP3 inflammasome, consisting of NLRP3, ASC, and caspase-1, is activated in response to SARS-CoV-2 infection and is active in COVID-19 patients, which is associated with the clinical outcome of the disease." (PMID 35655782, 2022). "In conclusion, COVID-19 and RA are both capable of high expression of activated caspase-1 in peripheral blood and tissues." (PMID 36532040, 2022). "Ongoing pyroptosis was also found in circulating monocytes from COVID-19 patients with increased caspase-1 activation and lytic death." (PMID 35655782, 2022). "The genes related to minocycline were then obtained by network pharmacology analysis and intersected with COVID-19, RA, and pyroptosis to obtain the common hub gene, and then the key gene was verified as CASP1 by two validation sets." (PMID 36532040, 2022). "In this study, immune cell infiltration analysis of COVID-19, RA, and the key gene for pyroptosis (CASP1) was found to be positively correlated with Monocytes, and the reliability of the results was verified by the HPA dataset and Monaco dataset databases." (PMID 36532040, 2022). "We conclude that caspase-1 is an interesting target for developing other potential drugs active against COVID-19." (PMID 35163769, 2022). "PBMCs from patients with COVID-19 exhibit active intracellular caspase-1, increased expressions of NLRP3 and ASC, and the secretion of IL-1β." (PMID 34360684, 2021). "High concentrations of active caspase-1 were detected in the sera of COVID-19 patients, and this increase was found to be more prominent in patients with the severe form." (PMID 34977191, 2021). "We also observed higher levels of caspase-1 adjacent to endothelial cells in the COVID-19 samples demonstrating endothelial infection, pyroptosis and injury in these patients." (PMID 34804033, 2021).
COVID-19 (continued). "We observed that the frequencies of FLICA caspase-1+ MAIT cells were significantly increased in the peripheral blood of patients with COVID-19." (PMID 34394094, 2021). "Clinically, circulating monocytes isolated from patients with severe COVID-19 exhibit increased caspase-1 activation and higher levels of lytic cell death compared with monocytes from healthy controls." (PMID 34360684, 2021). "Significant increases in the CASP1 expression in patients with acute COVID-19 were reported in previous transcriptomic studies." (PMID 34975885, 2021). "In particular, caspase-1 expression is distinct in CD4+ T lymphocytes in hospitalized patients with COVID-19." (PMID 34360684, 2021). "Patients with COVID-19 show high concentrations of active/cleaved caspase-1 and IL-18 in their sera." (PMID 34360684, 2021). "These aggregates are required for caspase-1-mediated IL-1 and IL-18 secretion, highlighting the role of CD14highCD16− monocytes in COVID-19-related inflammation." (PMID 35095880, 2021). "We have shown that COVID-19 patients display elevated caspase-1 activity and accumulation of lipid peroxides in circulating CD14highCD16− monocytes." (PMID 35095880, 2021). "The pan-caspase inhibitor emricasan inhibited the caspase-1 activity of CD4+ T lymphocytes in the blood of patients with moderate to severe COVID-19." (PMID 34360684, 2021). "To clinically validate our findings, we evaluated if monocytes obtained from critically ill patients with COVID-19 would also display signals of pyroptosis-like caspase-1-dependent cell death." (PMID 33649297, 2021). "Herein, we found an enrichment of CD14highCD16− monocytes displaying inflammasome activation evidenced by caspase-1/ASC-speck formation in severe COVID-19 patients when compared to mild ones and healthy controls, respectively." (PMID 35095880, 2021). "We observed that monocytes from COVID-19 patients had increased caspase-1 activation and significantly higher lytic death, by PI+ staining, when compared to monocytes from healthy donors (HD)." (PMID 33649297, 2021). "We observed higher caspase-1/4/5 activity within the classical monocyte subset from COVID-19 patients when compared to HCs, suggesting this cell subset contributes to IL-1β and IL-18 maturation during COVID-19." (PMID 35095880, 2021). "Herein, we expand this knowledge by showing that approximately 10% of circulating CD14highCD16− inflammatory monocytes from COVID-19 patients demonstrate ASC/Caspase-1/4/5 inflammasome complex formation, which appears to persist after short-term recovery." (PMID 35095880, 2021). "We next sought to investigate the crosstalk between the oxidative stress pathway and NLRP3-caspase-1 activation on circulating blood monocytes during COVID-19." (PMID 35095880, 2021). "Recent data suggest early activation of the NLRP3 inflammasome in severe COVID-19; the formation of the end product caspase-1 was enhanced among patients who had unfavorable outcome." (PMID 33682678, 2021). "Additionally, patients with long-term COVID-19 symptoms also showed upregulated caspase-1 activity in CD4+ T-cells." (PMID 40051620, 2025). "Its elevated levels in the control group, combined with the lower expression of caspase-1, further support our hypothesis of greater inflammasome activation in obese individuals with COVID-19." (PMID 40004007, 2025). "Regarding IL18 and CASP1, to the best of our knowledge, a relationship of their polymorphisms with COVID-19 exacerbation has not been previously reported." (PMID 38612539, 2024). "Finally, we stained the pancreatic autopsy samples and confirmed the increased CASP1 expression in COVID-19 samples compared with control samples." (PMID 39232561, 2024). "Interestingly, the results were consistent with those in COVID-19; 27 of the IRGs were highly expressed in myeloid cells, except Icam1, Lyn, Cybb, Casp1, Gbp1, Vnn2, Socs3, Bcl2a1 and Lcn2 genes." (PMID 36817436, 2023).
COVID-19 (continued). "However, a previous report has shown that caspase-1 and IL-18 in serum correlate with COVID-19 severity." (PMID 37168848, 2023). "Upregulation of CASP1 in COVID-19 was reported in a prior report, consistent with our findings." (PMID 37228369, 2023). "In addition, enhanced plasma levels of pyroptosis markers were detected in COVID-19 patients, and the levels of caspase -1 and IL-18 in serum correlated with the degree of COVID-19 severity, particularly in elderly patients." (PMID 38439942, 2023). "Further CIBERSORT analysis demonstrated that the variations in the immune microenvironment of COVID-19 patients may be correlated with CASP1, CD4, and EIF2AK3." (PMID 37228369, 2023). "In vitro experimental studies showed that pan-caspase inhibitor emricasan (EMR) could reduce active caspase-1 in CD4+ T cells from COVID-19 patients." (PMID 36263178, 2022). "Thus, exploring the potential inhibition of caspase-1 by colchicine provides useful information to ameliorate the health condition of COVID-19 patients." (PMID 35163769, 2022). "An increased immunoexpression of the tissue biomarkers CASP-1, IL-33, ACE2, B1R and B2R was observed in the alveolar septum of the COVID-19 patients, associated with a higher density of IgE+ MCs, tryptase+ MCs and TB-stained MCs, in addition to the presence of intra-alveolar edema." (PMID 35163636, 2022). "Moreover, the active form of caspase-1 (p20 subunits) was detected in peripheral blood mononuclear cells (PBMCs) and sera from patients with COVID-19, directly indicating the mechanism of pro-interleukin activation." (PMID 35997950, 2022). "Thus, minocycline can counteract the “cytokine storm” inflammatory response and resist pyroptosis in patients with COVID-19 combined with RA by inhibiting the expression and activation of caspase-1." (PMID 36532040, 2022). "Upon activation, caspase 1 processes pro-IL-1β and pro-ΙL-18 into their functional cytokine forms, which initiate the production of several other cytokines such as IL-6, IL-8, and TNFα, all of them overexpressed in severe COVID-19." (PMID 36498845, 2022). "The expression of inflammasome components (cleaved IL-1β, cleaved-CASP1, ASC, and NLRP3) was increased in COVID-19 variants and overexpressed in COVID-19/B.1.1.7 patients (p < 0.05 compared with COVID-19/B.1 variant) as indicates the immunohistochemical composite score." (PMID 36498845, 2022). "Minocycline may counteract cytokine storm inflammation in patients with COVID-19 combined with RA by inhibiting caspase-1 expression." (PMID 36532040, 2022). "Indeed, a classical pan-caspase inhibitor, emricasan, has been recently reported to reduce caspase-1 activity in CD4+ T cells from patients with COVID-19 ex vivo." (PMID 35997950, 2022). "Caspase-1 is a common biomarker for COVID-19, RA, and pyroptosis, and it may be an important mediator of the excessive inflammatory response induced by SARS-CoV-2 in RA patients through pyroptosis." (PMID 36532040, 2022). "Exosomes from COVID-19 patients activate caspase-1 in endothelial cells." (PMID 35587188, 2022). "Through the higher values of CASP-1 tissue immunoexpression in COVID-19 patients, we could demonstrate the evidence of pyroptosis, leading to a possible induction of activation and degranulation of MCs." (PMID 35163636, 2022). "Regarding caspase targeting agents, the pan-caspase inhibitor Emricasan (EMR) was shown to attenuate caspase-1 hyperactivity in CD4+ T cells from COVID-19 patients ex vivo and the caspase-8 inhibitor Z-IETD-FMK subdued SARS-CoV-2-induced BID cleavage and caspase-3 activation." (PMID 35265086, 2022). "To investigate the association between pyroptosis, a newly identified programmed cell death pathway, and disease severity during SARS-CoV-2 infection, we first compared CASP1 gene expression and found the CASP1 gene expression in patients with COVID-19 showed higher levels than those in in HDs." (PMID 34394094, 2021).